S100A8 (S100 calcium binding protein A8)
Diseases named in the same sentence as S100A8 in open-access papers (continued):
Sharing a sentence is not in itself a finding about the gene and the disease.
psoriasis (continued). "The high expression of S100A8/A9 in psoriasis epidermis induces C3/CFB complement activation, which subsequently leads to uncontrolled immunocyte activation, angiogenesis and keratinocyte hyperproliferation." (PMID 29942307, 2018). "In psoriasis patients, S100A8 is mainly derived from keratinocytes and infiltrating mononuclear cells, and S100A9 is derived from neutrophils." (PMID 29942307, 2018). "Collectively, these data indicate that despite IMQ triggers a similar enhanced Th17-mediated response in immune cells from control and GILZ-Tg mice, it results in higher induction of the marker of psoriasis S100a8 in GILZ overexpressing keratinocytes." (PMID 27934944, 2016). "Additionally, si-Yap1 significantly decreased the expression of psoriasis-related genes, including S100a7, S100a8, and S100a9." (PMID 40108109, 2025). "S100A8/A9 might be involved in the development of high-risk coronary plaques in psoriasis.Through the regulation of complement factor C3, the S100A8/9 protein complex mediated psoriasis." (PMID 39480805, 2024). "Additionally, the expression of alarmins S100a8 and S100a9, which have been considered as reliable biomarkers for monitoring inflammatory disease activity in psoriasis, was also decreased." (PMID 38891893, 2024). "Furthermore, assessing the levels of S100A8, IL-18, and sE-selectin in saliva can also be useful, as these are potential biomarkers for diagnosing psoriasis." (PMID 39595528, 2024). "S100A8/A9 activates keratinocyte complement component protein 3 (C3) in psoriasis." (PMID 39420283, 2024). "A recent study has shown that disruption of the epidermal barrier can exacerbate psoriasis by unregulated keratinocyte proliferation and the overexpression of S100A8, S100A9, CXCL1, and other molecules, indicating a defect in ceramide-dependent epidermal barrier signaling and function." (PMID 36837912, 2023). "Other differentially methylated loci in psoriatic lesions compared with the normal skin of patients with psoriasis and with normal skin from healthy controls are S100A8 (involved in epidermal differentiation), CYP2S1 (metabolism of retinoic acid), and EIF2C2 (with a role in RNA processing)." (PMID 37628670, 2023). "Epidermal expression of S100A8 and S100A9 is a hallmark of psoriasis." (PMID 35812457, 2022). "S100A8, which is highly expressed in the lesion skin and serum of psoriasis patients, is produced by keratinocytes in the lesion skin and is thought to be involved in the pathogenesis of psoriasis via its chemotactic activity for neutrophils and CD4+ T lymphocytes." (PMID 36620087, 2022). "Interestingly, stress keratinocytes expressing KRT6, KRT16, and S100A8/9 have been identified in the human epidermis of psoriasis and melanomas, raising the possibility that they can play a wide variety of roles in the diseased skin TME." (PMID 35653192, 2022). "Serum levels of S100A8/S100A9 correlate with disease activity in psoriasis patients." (PMID 35812457, 2022). "The S100A8/A9 complex is a critical alarmin that is upregulated in numerous inflammatory diseases such as rheumatoid arthritis, chronic inflammatory bowel disease, psoriasis, systemic lupus erythematosus, and atopic dermatitis." (PMID 34642376, 2021). "Many of these genes, such as Defb4 and S100a8, are key players in the pathomechanism of psoriasis." (PMID 34440590, 2021). "S100A8 was positively correlated with psoriasis severity in the group with psoriasis (p<0.05)." (PMID 33531183, 2021). "The significant role of S100A8 in prognosis of psoriasis is also illustrated in the literature." (PMID 34267747, 2021). "Serum levels of S100A8/S100A9 show a close correlation to disease activity in psoriasis patients." (PMID 33643287, 2020). "Although the expression of S100A8/A9 complex is often restricted to myeloid cells, its induction has also been described in hyperproliferative and differentiated keratinocytes, such as during wound healing or in psoriasis lesions." (PMID 33031460, 2020).
psoriasis (continued). "In line with previous reports, we found a high expression of both proteins S100A8 and S100A9 in a murine model of IMQ-induced psoriasis which confirms also data obtained from human psoriatic lesions showing a strong increase of S100A8 and S100A9 expression in keratinocytes." (PMID 33643287, 2020). "Since etanercept treatment induces significant serum S100A8/A9 reduction in patients with psoriasis S100A8/A9 might be involved in the systemic anti-inflammatory effect of biologics." (PMID 30865695, 2019). "Further studies are required to identify the source of elevated serum S100A8/A9 levels, which could lead to a better understanding of systemic inflammation and comorbidities in psoriasis." (PMID 30865695, 2019). "Elevated S100A8/A9 serum levels serves as a sensitive biomarker of disease activity in different autoimmune diseases (e.g., rheumatoid arthritis, type I diabetes, and psoriasis)." (PMID 30105034, 2018). "For example, S100A4 is involved in autoimmune pancreatitis, S100A11, S100A8 and S100A9 in rheumatoid arthritis, S100A1 in hypoxia-induced inflammatory response in cardiomyocytes, S100A12 in Crohn’s disease, S100A7 and S100A7A in psoriasis, S100A8, S100A9 and S100A12 in systemic lupus erythematosus." (PMID 30018736, 2018). "Unexpectedly, in GILZ-Tg mice, the severity of IMQ-induced psoriasis-like skin lesions as well as induction of cytokines commonly up-regulated in human psoriasis (Il-17, Il-22, Il-23, Il-6, S100a8/a9, and Stat3) was significantly more pronounced relative to GILZ-Wt mice." (PMID 27934944, 2016). "Furthermore, in psoriasis, epidermal S100A8/A9 overexpression seems to be related to increase serum S100A8/A9 levels, which correlate with disease activity." (PMID 27537874, 2016). "However, in the rERDR1-injected group, the expression of Krt6, Krt14, Krt16 and S100a8 was significantly decreased, demonstrating that rERDR1 inhibits the induction of psoriasis-like skin inflammation by imiquimod." (PMID 26901187, 2016). "The mRNA expression of Krt6, Krt14, and Krt16 which are associated with hyper-proliferation of keratinocytes, and of antimicrobial peptide S100a8, which is correlated with psoriasis severity, were significantly increased by imiquimod treatment in the vehicle (PBS)-injected group." (PMID 26901187, 2016). "This hypothesis is supported by previous studies; for example, the S100A8/A9 complex is significantly elevated in psoriasis serum and positively correlates with disease activity, while CXCL8 inhibitors can significantly reduce intestinal inflammation in animal models." (PMID 40540498, 2025). "Furthermore, psoriasis treatment has been shown to reduce S100A8/A9 levels." (PMID 38256115, 2024). "Furthermore, the relevance of the feedback between TNF-α and S100-proteins has been confirmed for inflammatory processes like arthritis and psoriasis and IL-6 is the top cytokine induced by S100A8/S100A9 in myeloid cells as shown in a genome wide transcriptome analysis." (PMID 37056775, 2023). "S100A8/A9 may, therefore, be a promising predictive marker of psoriasis severity." (PMID 36235175, 2022). "S100A8 may thus serve as a biomarker for the effectiveness of anti-psoriatic drugs, and combination therapies with solenopsin analogs and other modalities for psoriasis, such as glucocorticoids and UV light, may lead to long-term remission." (PMID 28894119, 2017). "In addition, S100A8 is also a well-described and well-known psoriasis-inducing gene." (PMID 27774448, 2016). "In all five mouse phenotypes, there was increased expression of S100a9, Lcn2, S100a8, Sprr1b, Mpzl2, Has3, as well as decreased expression of Tppp, Stxbp6, and Cldn23, and each of these effects is consistent with characteristic expression patterns in clinical psoriasis." (PMID 21483750, 2011).
psoriasis (continued). "Research has indicated that S100A8 and S100A9 are highly expressed in autoimmune diseases such as Rheumatoid Arthritis (RA), Systemic Lupus Erythematosus (SLE), Psoriasis (Pa) and Juvenile Idiopathic Arthritis (SoJIA)." (PMID 39877611, 2025). "The expression of S100a8 and S100a9 was increased in IMQ-induced psoriasis both in bulk RNA-seq and scRNA-seq." (PMID 38472183, 2024). "In psoriasis, S100A7, S100A8, S100A9, S100A12, and S100A5, defined as “antimicrobial peptides”, are the main S100 family members involved." (PMID 38255845, 2024). "In contrast, both S100A8 and S100A9 are significantly increased in the serum and damaged skin of psoriasis patients." (PMID 38255845, 2024). "We analyzed ScRNA-seq dataset GSE162183 from Gao’s study and found that both S100A8 and S100A9 were among the top 10 molecules expressed in lesional skin tissue of psoriasis patients, with notably high expression in keratinocytes." (PMID 38429278, 2024). "Following the decrease in Livin expression, a substantial reduction was observed in the levels of inflammatory mediators, namely, MMP‐7, Cath B, CXCL 6, S100A8, S100A7, and S100A11, which have crucial functions in psoriasis." (PMID 38332513, 2024). "The PPI results and friends analysis demonstrated strong correlations between S100A9, S100A8, NAMPT, TYMP and others, suggesting their potential involvement in the regulation of PANoptosis in psoriasis." (PMID 39480805, 2024). "Other studies suggest that S100A8/A9 heterodimer and S100A8/S100A9‐tetramers also exert anti‐inflammatory effects, in the context of MI, psoriasis and arthritis lesions." (PMID 38504474, 2024). "After IL-17A blockade, KC expression of IL36G, S100A8, DEFB4A, and DEFB4B in S. corneum and S. granulosum decreased in posttreatment psoriasis lesional skin compared to pretreatment psoriasis lesional skin (p < 0.05)." (PMID 37781383, 2023). "S100A7, S100A8, and S100A9 were markedly over-expressed in all three layers in PP, consistent with previous psoriasis studies." (PMID 37308489, 2023). "After systemic IL-17A blockade, the expression of those inflammatory mediators (IL36G, S100A8, DEFB4A, and DEFB4B) was decreased in posttreatment psoriasis lesional skin KCs compared to pretreatment psoriasis lesional skin KCs (p < 0.05)." (PMID 37781383, 2023). "The expression of IL-17-driven inflammatory mediators (IL36G, S100A8, DEFB4A, and DEFB4B) in suprabasal keratinocytes was correlated with psoriasis severity and was downregulated by IL-17A blockade." (PMID 37781383, 2023). "The expression levels of several S100 proteins, such as S100A2, S100A7, S100A8/S100A9, S100A12, and S100A15, are significantly up-regulated in psoriasis-involved skin." (PMID 37346040, 2023). "The expression of inflammatory mediators induced by IL-17 in keratinocytes (IL36G, S100A8, DEFB4A, and DEFB4B) was increased in pretreatment psoriasis lesional skin KCs compared to control skin KCs (p < 0.05)." (PMID 37781383, 2023). "Among these proteins, well-known circulating markers for psoriasis such as P-selectin (P16109), S100A8 (P05109), S100A9 (P06702), and talin-1 (Q9Y490) were found to be upregulated in patients with psoriasis compared to healthy control." (PMID 36804462, 2023). "SerpinB7 knockdown in HaCaT cells drastically increased the expression of psoriasis-related chemokines (CCL20, CCL27, CXCL1, CXCL2) and antimicrobial peptides LL37 and S100A8 in the M5-stimulated in vitro psoriatic model." (PMID 35864103, 2022). "In support of the Role of IL-17A in the Psoriasis Pathway, CXCL1, CXCL3, CXCL6, S100A8, S100A9, and CCL20 in the shared signature were all upregulated in both psoriatic skin and colon lesional tissues." (PMID 36396672, 2022). "S100A8 and S100A9 are thought to be characteristic of several acute and chronic inflammatory disease, including psoriasis, inflammatory bowel disease, and rheumatoid arthritis." (PMID 34934042, 2021).
psoriasis (continued). "Psoriasis-related genes in HaCaT cells, such as S100A7, S100A8, and S100A9, were downregulated by miR-193b-3p overexpression in the presence or absence of M5 treatment." (PMID 34667159, 2021). "S100A8 and S100A9 were robustly upregulated in skin tissues under pathological conditions, such as psoriasis, atopic dermatitis, and wounds, and they contributed to development of these pathological processes." (PMID 34099591, 2021). "High abundance of these S100-proteins during psoriasis can be explained especially by the effects of IL-17A, IL-17F, TNF, and IL-1α on S100A8/S100A9 expression, which are all central players in the pathogenesis of psoriasis." (PMID 33643287, 2020). "During dermal inflammation or wound healing complexes of S100A8 and S100A9 are expressed and released by keratinocytes and activated leukocytes especially in psoriasis lesions." (PMID 33643287, 2020). "S100A7 (psoriasin), S100A8 (calgranulin A), S100A9 (calgranulin B), S100A12 (calgranulin C), and S100A15 are highly expressed in psoriasis." (PMID 33050592, 2020). "We next analyzed the expression patterns of S100A8 and S100A9 in 25 paired samples of psoriasis treated with IL-17 directed therapy (700 mg of brodalumab) or placebo (GEO accession ID GSE53552)." (PMID 33643287, 2020). "S100A8 and S100A9 are exceedingly upregulated in the epidermis in lesional skin of patients with psoriasis and histopathological analysis of psoriatic lesions show increased levels of S100A8/A9 in keratinocytes compared to healthy skin." (PMID 30865695, 2019). "The correlation between psoriasis area and severity index (PASI) and serum levels was studied to investigate a potential role of serum S100A8/A9 as a biomarker for skin disease severity." (PMID 30865695, 2019). "S100A8 and S100A9 proteins are highly upregulated in patients with psoriasis and have been proposed as potential biomarkers for psoriasis." (PMID 30865695, 2019). "This is the reason why S100A8 and S100A9 are strong protein candidates for therapeutic targeting of psoriasis and PsA." (PMID 31275060, 2019). "Several S100 proteins and particularly S100A8 and S100A9 are highly upregulated in psoriasis plaques." (PMID 30865695, 2019). "Several genes reported to be involved in psoriasis pathogenesis including S100A9, S100A8, PTPN22, PTPN6, LAMA4, IL1B and IL12RA were involved in many of these enriched biological processes." (PMID 30092825, 2018). "S100A8 and S100A9 are antimicrobial peptides that form a heterodimer called calprotectin which interacts with Toll-like receptor 4 (TLR-4) and exacerbates psoriasis by activating complement factor C3 and recruiting neutrophils." (PMID 30279326, 2018). "S100A7 (psoriasin), S100A8 (calgranulin A), S100A9 (calgranulin B), and S100A12 (calgranulin C) are markedly increased in psoriasis lesions." (PMID 29619128, 2018). "Results from qRT-PCR measurements of psoriasis-relevant transcripts showed that levels of DEFB4B, IL36G, LCN2, S100A7, S100A8 mRNA were significantly decreased in rhodomyrtone-treated cultures when compared with cytokine-treated cultures (p<0.0001, all)." (PMID 30321197, 2018). "Therefore, ERDR1-regulated S100A8 may be involved in angiogenesis in the psoriasis mouse model." (PMID 26901187, 2016). "Psoriasin, S100A8 (calgranulin A) and S100A9 (calgranulin B) are expressed in ductal carcinoma in situ (DCIS), as well as in the hyperproliferative skin disease, psoriasis." (PMID 17986321, 2007). "The activation and activity of S100A8 and S100A9 is an indicator of psoriasis and may indicate the response of the immune system to psoriasis." (PMID 40540498, 2025). "Furthermore, a study showed that S100A8 and S100A9 can regulate psoriasis by inhibiting production of the IL-17 A and IL-17 F." (PMID 39095779, 2024). "Recently, S100A8 and S100A9 were proven to contribute to psoriatic skin inflammation and could be a biomarker of psoriasis severity." (PMID 38429278, 2024).
psoriasis (continued). "When we compared KC transcriptome in different epidermal layers, the expression of IL-17-driven inflammatory mediators (IL36G, S100A8, DEFB4A, and DEFB4B) was localized to suprabasal layers (S. corneum, S. granulosum, and S. spinosum) in pretreatment psoriasis lesional skin." (PMID 37781383, 2023). "Expression levels of S100A8 and S100A9 are significantly elevated in psoriatic keratinocytes and leukocytes, and their expression levels correlate positively with the severity of psoriasis." (PMID 37346040, 2023). "In addition, serum S100A8 and S100A9 levels are increased in psoriasis and positively correlated with PASI score, indicating that their production is positively correlated with disease development in psoriasis." (PMID 37891988, 2023). "The transcriptional expressions of Cxcl1, Cxcl2, Il-1β, Il-1α, S100A8, S100A9, Il-6, and Vegf were significantly decreased in skin lesions of K14.Bsgfl/fl mice, indicating the proinflammatory role of the epidermal expression of CD147 in psoriasis." (PMID 37303600, 2023). "The mechanisms of S100A8 and S100A9 in psoriasis were revealed to some degree in previous studies." (PMID 37891988, 2023). "Members of the S100 family of proteins intensively studied in the course of psoriasis include S100A4 (Figure A1), S100A7 (Figure A2), S100A8 (Figure A3), S100A9 (Figure A4), S100A12 (Figure A5), S100B (Figure A6) and S100A15, indicating their involvement in the pathogenesis of the disease." (PMID 36235175, 2022). "To understand the molecular mechanism of N4BP1 in the regulation of neutrophil infiltration, we examined the mRNA level of several key genes involved in inflammation including TNFa, IL-23, IL-17, CXCL1, CCL20, S100A8, and S100A9 in psoriasis skin from N4BP1 KO and WT mice." (PMID 33990547, 2021). "The comparison of microarray datasets of psoriasis resulted in one common DEG, named S100A8." (PMID 34267747, 2021). "Parallel with the expression of S100A8 and S100A9 IMQ-treated mice developed psoriasis features like erythema, scaling, thickening of skin, parakeratosis, acanthosis of the epidermis, signs of hyperproliferation of keratinocytes, and increased numbers of basal keratinocytes." (PMID 33643287, 2020). "S100A8 and S100A9 have manifold inflammatory activities, which may amplify disease activity in psoriasis." (PMID 33643287, 2020). "Serum S100A8/A9 levels do not correlate with PASI questioning serum S100A8/A9 as a biomarker for psoriasis skin activity." (PMID 30865695, 2019). "S100A8/A9 has become a widespread biomarker used in the diagnosis and monitoring of inflammatory bowel disease (IBD) and has been proposed as a potential biomarker for psoriasis and psoriasis arthritis (PsA)." (PMID 30865695, 2019). "For instance, S100A8 and S100A9 form a complex called calprotectin that aggravates psoriasis by regulating expression of the C3 complement factor, while hBD-2 promotes chemotaxis of various leukocytes in a C-C chemokine receptor (CCR) 2- and CCR6-dependent manner." (PMID 30918469, 2019). "In addition, disease severity was measured by psoriasis area and severity index (PASI) and serum protein levels of S100A8/A9 were repeatedly analyzed." (PMID 30865695, 2019). "Elevated S100A8/A9 levels in these studies were associated with increased risk for cardiovascular disease implicating that increased S100A8/A9 serum concentrations could be a marker of systemic inflammation rather than skin inflammation in individuals with psoriasis." (PMID 30865695, 2019). "Serum S100A8/A9 levels do not respond to treatment suggesting that serum S100A8/A9 does not originate from psoriasis skin keratinocytes." (PMID 30865695, 2019). "Hence, potential roles for S100A8 and S100A9 both as treatment targets and biomarkers for psoriasis disease severity have been proposed." (PMID 30865695, 2019).